PROM1 (prominin 1)
Diseases named in the same sentence as PROM1 in open-access papers (continued):
Sharing a sentence is not in itself a finding about the gene and the disease.
cancer (continued). "Pretreatment with gigantol decreased the levels of cancer stem cell markers, including prominin-1 (CD133) and aldehyde dehydrogenase 1 family member 1A (ALDH1A1), in A549, H460, and H292 cells." (PMID 34279440, 2021). "To assess the impact of PROM1/PROM2 co-expression on various cancers, we performed several multivariate survival analyses on OncoLnc, using TCGA data." (PMID 31164716, 2020). "These clinical findings underscore the potential importance of PROM1+ cells in chronic liver disease and cancer." (PMID 33173221, 2020). "CD133 (also known as Prominin-1) is encoded by the PROM1 gene and localizes to membrane protrusions of normal and cancer cells." (PMID 32429463, 2020). "While PROM1 is broadly reported and recognized as a marker for cancer stem cells, few studies have investigated the biological function of PROM2." (PMID 32123287, 2020). "PROM1 is a well-known marker of TICs in many cancers and used to define cancer stemness and disease severity in patients." (PMID 33173221, 2020). "PROM1 (CD133) is widely known as a biological marker for cancer stem cells of certain cell types, and is present in epithelial and non-epithelial cells." (PMID 32123287, 2020). "In our systematic analysis, we also found several missense and truncating mutations within PROM1 and PROM2 protein-coding sequences, especially in the prominin domain, in various cancer types." (PMID 31164716, 2020). "The pattern of PROM2 expression in different types of cancers was considerably different to the expression pattern of PROM1." (PMID 31164716, 2020). "We analyzed genetic alterations of PROM1 in different cancers using cBioPortal and compared the results with those of other genes of interest mentioned in the preceding subsection." (PMID 31164716, 2020). "Among the CRC-cell line markers, the Caco-2 line-specific EV protein Prominin-1 (PROM1), CD133, is a marker of cancer stem cells and associated with metastasis in CRC, and PROM1 overexpression renders tumors resistant to chemotherapy and radiation therapy." (PMID 32916986, 2020). "Prominin 1 (PROM1) is considered a biomarker for cancer stem cells, although its biological role is unclear." (PMID 31164716, 2020). "Accumulating evidence suggests that several factors, including DNA hypomethylation and hypoxia, affect PROM1 expression in cancer cells." (PMID 31164716, 2020). "Expression of cancer stemness markers (PROM1 and LGR5), EMT genes (SNAI1, ZEB1 gene and CDH1) and percentage of ALDH + cells were evaluated to assess the effect of sinensetin in modulating cancer stemness and self-renewal." (PMID 33628166, 2020). "Proposed cancer stem cell (CSC) markers are prominin-like protein 1 (PROM1), also known as CD133, aldehyde dehydrogenase 1 (ALDH1), as well as members of the ABC transporter family." (PMID 33322555, 2020). "Another cell surface marker CD133/Prominin-1 has also been identified as a biomarker for CSC in various cancers, including HCC." (PMID 32408542, 2020). "CD133, the glycoprotein also known as prominin-1, is another well-known marker on the CSCs surface and it has been reported to be a useful target in cancers with a large CD133 subpopulation." (PMID 31709180, 2019). "The CD133 signature genes included PROM1, which encoded CD133 molecules (“CD133-up”), and OVOL2, whose encoded transcription factors have been previously implicated in epithelial differentiation and cancer progression (“CD133-down”)." (PMID 30717708, 2019). "If and how Prom1 can be used as a molecular biological tool in regulating stem cells for regenerative medicine and anti‐cancer therapies are still uncertain." (PMID 30523147, 2019). "In general, cancer stem cells (CSCs) express prominin-1 (CD133), considered as a potential therapeutic target." (PMID 31275378, 2019). "Of these, ALDH1A3, TM4SF1, and PROM1 were identified as cancer stem cell markers and CAV1 was EMT‐related." (PMID 31498560, 2019).
cancer (continued). "CD133, also called Prominin-1, is a pentaspan transmembrane protein which has been used as a biomarker to identify and isolate stem cells from cancer tissues, including those emerging from colorectal mucosa." (PMID 31139149, 2019). "As a cancer stem cell marker, PROM1 was identified as both a hematopoietic and neuroepithelial stem cell marker." (PMID 30177858, 2018). "CD133 (Prominin-1) is an important cell surface marker of cancer stem (like) cells (CSCs) in various cancers, including CRC." (PMID 29100290, 2017). "From this list, 8 novel top candidate genes were selected based on their display of highly cancer-specific hypermethylation over multiple adjacent promoter-associated DMCs: COL4A6, CYBA, HLF, LINC0134 (LOC149234), LRRC4, PROM1, RHCG, and TCAF1 (FAM115A)." (PMID 28052017, 2017). "The pentaspan membrane glycoprotein prominin-1 (CD133) is widely used in medicine as a cell surface marker of stem and cancer stem cells." (PMID 27701459, 2016). "The detection of prominin-1 in human cancer-initiating cells from various organs brought an international interest to this molecule as a specific biomarker of cells with stem cell properties, and, excitingly, as a potential target for cancer eradication." (PMID 27701459, 2016). "Given the growing interest of prominin-1 as a biomarker of stem and cancer stem cells and dogs as experimental models, it is important to generate specific mAbs against canine prominin-1." (PMID 27701459, 2016). "It regulates the expression of CD133 (gene symbol: PROM1) in cancer stem cells (CSCs) by DNA methylation." (PMID 25814785, 2015). "A large body of publications mentioning prominin-1 (Prom1, CD133) is related to its use as a stem and cancer stem cell marker." (PMID 25954606, 2015). "Cancer stem cells are detected by a number of cell surface markers including CD133 (prominin 1) and CD166 both of which were already known to define stem and progenitor cells." (PMID 26649310, 2015). "Expression of Prominin-1 (CD133), a marker for cancer stem cells, was enhanced with the days of culture." (PMID 26167183, 2015). "In most tissues, prominin-1 was partially co-expressed with two cancer markers: carcinoembryonic antigen (CEA) and mucin-1 (MUC1)." (PMID 24911657, 2014). "ARID3B induced expression of genes associated with metastasis and cancer stem cells (CD44, LGR5, PROM1 (CD133), and Notch2)." (PMID 25327563, 2014). "prominin-1–positive cancer stem cells were shown to be resistant both to radiotherapy and chemotherapy." (PMID 24911657, 2014). "Given the growing body of publications suggesting a role for prominin-1 and syntenin-1 in cancer progression and metastasis their interaction under normal and pathological conditions deserves particular attention in a near future." (PMID 24911657, 2014). "Generally CD133 antigen has been less effective as a cancer stem cell marker in mice than humans, possibly related to the differences we have found in the cells expressing Prom1." (PMID 25184684, 2014). "The pentaspan membrane glycoprotein CD133 (also known as prominin-1) has been widely used as a marker for both cancer and normal stem cells." (PMID 23326490, 2013). "Subsequently, CD133 (prominin-1), a transmembrane protein with uncertain biologic function, became the most common marker used to identify cancer stem cells from a variety of diverse adult and pediatric solid tumors including HGGs." (PMID 23450706, 2013). "PROM1 transcripts initiate at a range of transcription start sites (TSS) associated with distinct tissue and cancer expression profiles." (PMID 24194746, 2013). "PROM1 is the gene encoding prominin-1 or CD133, an important cell surface marker for the isolation of both normal and cancer stem cells." (PMID 24194746, 2013). "CD133/Prominin-1 is a pentaspan transmembrane protein that has been frequently used as a biomarker for cancer stem cells, although its biological function is unclear." (PMID 23437259, 2013).
cancer (continued). "Recent studies have demonstrated that CD133 (prominin-1) is a specific marker of CSCs in a wide spectrum of malignant tumors." (PMID 24212663, 2011). "Altogether, these preliminary observations highlight a functional role of CD133/prominin-1 in sustaining a stem cell phenotype, and support this molecule as a central target for successful cancer therapy." (PMID 24212957, 2011). "Prominin-1, a heavily glycosylated pentaspan membrane protein, is mainly known for its function as a marker for (cancer) stem cells, although it can also be detected on differentiated cells." (PMID 20808829, 2010). "The human orthologue of prominin-1, called CD133 has been used as a marker in a variety of cancers to isolate cancer stem cells (CSCs) as well as hematopoietic stem cells." (PMID 20808829, 2010). "Basal-A lines were characterized by expression of PROM1 (aka CD133), a marker of various cancer stem cells, as well as other genes like GABRP and VTCN1." (PMID 19582160, 2009). "CD133 (prominin-1), a 5-transmembrane glycoprotein, has recently been considered to be an important marker that represents the subset population of cancer stem-like cells." (PMID 18612434, 2008). "Since interleukin-6/STAT3 signaling is known to stimulate prominin-1 expression, prominosome-mediated cancer cell–macrophage communication could create a positive feedback loop that further enhances cancer growth and metastasis." (PMID 39881297, 2025). "CD133, also known as prominin-1, and stage-specific embryonic antigen-4 (SSEA4), both were recognized as potential CSC markers, and have been linked to stemness and chemoresistance in a variety of cancers, including BC8,9." (PMID 40369257, 2025). "Further research on prominosomes could be of clinical interest, especially because of the relevance of prominin-1 as a stem and cancer stem cell marker." (PMID 39881297, 2025). "However, the intracellular localization of prominin-1 in endosomal compartments of some cells, notably HSPCs and cancer cells, suggests an additional source for such small EVs." (PMID 39881297, 2025). "CD133, also known as Prominin-1, is a transmembrane glycoprotein predominantly expressed on the apical membrane protrusions of embryonic epithelial cells and various stem-like cancer cells." (PMID 40429879, 2025). "For this reason, PROM1 has been widely studied as a target for cancer therapeutics." (PMID 40650074, 2025). "CD133 (also called Prominin-1) is a pentaspan transmembrane glycoprotein widely used for stem and progenitor cell identification in several normal tissues and cancer stem-like cells of different types of cancer." (PMID 37922108, 2024). "These interactions are crucial for understanding the role of Prominin-1 in cancer development." (PMID 39409917, 2024). "CD133 is a single-chain transmembrane glycoprotein encoded by the prominmin 1 gene (PROM1), and it is expressed on immature haematopoietic stem cells, tissue-specific progenitor cells, and cancer stem cells." (PMID 38365731, 2024). "PROM1 encodes CD133, which is a marker of cancer stem cells and de-differentiation." (PMID 38287344, 2024). "CD133/Prom1 is a well characterized adult and cancer stem cell marker in many tissues." (PMID 37605939, 2023). "The CD133 antigen, also known as Prominin 1, is frequently used to isolate cancer stem cells." (PMID 36769824, 2023). "Specific surface markers of cancer stem cells, such as the stem cell marker Prominin-1 (CD133), Octamer-binding transcription factor 4 (OCT4), Transcription factor SOX-2 (SOX2), and Homeobox protein NANOG (NANOG), are frequently used for classifying cancer stem cells." (PMID 36769824, 2023).
cancer (continued). "PROM1 (CD133) is an enrichment within PDAC lines despite its function in cancer invasion." (PMID 36653361, 2023). "PROM1 is well known as a marker for cancer stem cells and normal stem cells." (PMID 36266314, 2022). "Remarkably, some cancer stem cell genes were also found in this group, such as PROM1 (also known as CD133) which is a member of a prominent family of pentaspan transmembrane glycoproteins of murine neuroepithelial origin (typically located in plasma membrane protrusions)." (PMID 35054064, 2022). "In addition to cancer stem cells, PROM1 is also expressed in normal stem cells, including hematopoietic stem cells and various epithelial cells, in the brain, kidney, digestive track, and liver." (PMID 36266314, 2022). "By examining the expression pattern of cancer stem cells markers (e.g., PROM1, CD44, and EPCAM), it is found that CD44 positive population may render drug resistance in HCC272." (PMID 34105295, 2021). "CD133 or Prominin-1 is a membrane-anchored and cell surface protein first discovered in mouse and human stem cells, which indicates the presence of cancer stem cells in tumorous tissue." (PMID 34837909, 2021). "Moreover, PROM1 regulates metastasis, drug resistance, and stemness properties in various cancer cells." (PMID 31164716, 2020). "Furthermore, the monoubiquitination of the cancer stem cells marker CD133 (prominin-1) promotes its secretion into extracellular vesicles by facilitating the interaction of CD133 with the vesicular sorting protein tumor susceptibility gene 101 (TSG101)." (PMID 32344852, 2020). "Therefore, we investigated the patterns of expression, mutation, and copy number alteration of PROM1 and PROM2 genes to determine their clinical significance in human cancers through systematic data analysis." (PMID 31164716, 2020). "SOX2, BMI-1, and PROM1 are cancer stem cells-related genes, and TWISTNB is implicated in EMT." (PMID 32118031, 2020). "CD133 is trans-membranous protein Known also as prominin-1 which express in the vast majority of stem cells and if be positive definitely simulates CSCs properties and it is approved in an animal model of cancer in NOD/SCID mice." (PMID 32665892, 2020). "The cell surface marker CD133 (prominin-1), initially recognized as a surface marker for hematopoietic and neural stem cells, has been successfully used to enrich for cells with stem cell or cancer-initiating characteristics from multiple organs." (PMID 31828551, 2019). "Prominin-1 (CD133), a membrane glycoprotein associated with LR-membrane vesicles, has been identified as a marker of neuronal cells, immature hematopoietic stem cells, and cancer stem cells." (PMID 31234505, 2019). "Similarly, another gene involved in the stemness maintenance of cancer cells, PROM1, can also have differential expression patterns." (PMID 29534550, 2018). "To find out whether a relation between the expression of prominin-1 and other cancer markers such as CEA and MUC1 exists, we re-examined our samples with specific and characterized antibodies." (PMID 24911657, 2014). "Expression of Prom1 in cancer is thought to parallel expression and function in normal stem cells." (PMID 25184684, 2014). "The subcellular localization of prominin-1 might also be instructive about the origin and progression of cancers." (PMID 24911657, 2014). "Recent studies have highlighted the importance of syntenin-1 in metastatic dissemination of malignant tumors suggesting that prominin-1–syntenin-1 complex might be involved in disease progression." (PMID 24911657, 2014). "Prom1-exo, homogenous cancer organelles expressing a cancer stem cell marker, are more likely to have a concordant message(s), and this makes them especially interesting to gain insight into the mechanisms by which exosomes contribute to the malignant phenotype." (PMID 23767874, 2013). "This is the first report of prominin-1-based purification of cancer exosomes." (PMID 23767874, 2013).
cancer (continued). "We identify a previously unknown promoter that shows differential expression and regulation of PROM1 mRNA in restricted tissues, stem-like cells within cancer cell lines and stem cells." (PMID 24194746, 2013). "These promoters differentially regulate expression of PROM1 in adult tissues and cancer cell types." (PMID 24194746, 2013). "Indeed, the variability in PROM1 expression in primary ESFT combined with the inconsistent biologic properties of CD133+ ESFT cells in culture suggest that CD133 expression alone will be insufficient to isolate drug-resistant cancer stem cells in ESFT." (PMID 20346143, 2010). "CD133 (Prominin-1) is a cell surface marker of cancer stem cells." (PMID 17615543, 2007). "However, prominin-1 is expressed by endothelial progenitors and, if neovasculogenesis occurs during cancer progression, those cells may contribute to the release of prominosomes." (PMID 39881297, 2025). "Moreover, principal component analysis of single-cell RNA-sequencing data of 65,655 GSCs and 14,207 GBM cells revealed that the area where CYP3A5 was highly expressed harbored cells that also markedly expressed cancer stem cell markers, such as PROM1, SOX2, EZH2 and NOTCH1." (PMID 39754188, 2025). "Given that prominin-1 is upregulated in various cancers, monitoring the amount of prominosomes in a given body fluid can be highly informative and they may be used as a potential cancer biomarker." (PMID 39881297, 2025). "Similarly, genes coding for multiple cytokines and surface protein markers that are known to be associated with the basal phenotype, pluripotency, and cancer aggression, such as CD44, KIT, EGFR, and PROM1, were also significantly upregulated in the BORGHigh tumors." (PMID 39335212, 2024). "Prominin-1 (CD133), the first member of the prominin family, was first identified in 1997 by two independent study groups examining mouse neuroepithelial and human haematopoietic stem cells, and it was stated that prominin-1 was a common cell surface marker of both stem cells and cancer stem cells." (PMID 37841777, 2023). "Thus, PROM1 has been considered a very important target protein for cancer therapy." (PMID 36266314, 2022). "Interestingly, the reactivity of the AC133 antibody, a reagent commonly used to detect the human PROM1 protein, is reduced during cancer stem cell differentiation without corresponding loss of the protein." (PMID 36215230, 2022). "Importantly, targeting prominin-1 might, beyond impacting prominin-1 expressing cells, also alter prominin-1+ vesicle-mediated intercellular communication within the cancer stem cell microenvironment." (PMID 34476215, 2021). "Furthermore, we aimed in the present study to evaluate the expression of nestin, NGFR, Sox10, FZD6 and PROM1 cancer stem cell markers and angiogenic factors in UM and to better understand the relationships between the detected markers and vasculogenic mimicry patterns." (PMID 33255843, 2020). "Interestingly, PROM1 has previously been reported as a cancer stem cell marker in CRC." (PMID 27935967, 2016). "Furthermore, does expression of Prom1 contribute to the maintenance of “cancer stemness”?" (PMID 25452936, 2014). "Despite PROM1 having a poor prognostic value as a cancer stem cell marker, our finding that PROM1 expression is anti-correlated with IDH1 mutations supports a different biology for IDH mutant tumors and indicates that PROM1 expression may be most relevant in the non-IDH mutant setting." (PMID 25184684, 2014). "The abundance of tetraspanins and of tetraspanin-associated proteins, together with the high levels of sphingomyelin, suggests that proteolipidic assemblies, probably tetraspanin webs, might be the essential structural determinant in the release process of prominin-1 of stem and cancer stem cells." (PMID 23767874, 2013).